FBLN5 (fibulin 5)
Diseases named in the same sentence as FBLN5 in open-access papers (continued):
Sharing a sentence is not in itself a finding about the gene and the disease.
Stroke (2 papers, 2022 to 2024). Sudden impairment of blood flow to a part of the brain due to occlusion or rupture of an artery to the brain. "Key EMT-related genes that were downregulated in female MMP-3 KO stroke brains included Fbln5, Fbln1, Fbln2, and Tgfb1." (PMID 39000490, 2024). "Key EMT-related genes that were downregulated in MMP-3 KO males included Fbn1, Fbln1, Tgfb1, Tgfbr3, Snai2, and Fgf2, while female MMP-3 KO stroke brains showed downregulation of Fbln5, Fbln1, Fbln2, and Tgfb1." (PMID 39000490, 2024). "Both male and female MMP-3 KO stroke brains showed decreased expression of genes involved in fibulin signaling (Fbln1, Fbn1, Fbln2, Fbln5), which are known to induce EMT during embryonic development." (PMID 39000490, 2024).
ascending aortic dilatation (1 paper, 2024). "Given that Fbln5 −/− mice develop severe arterial elastopathy in the absence of aneurysmal dilatation or dissection, preserving the integrity of the elastic laminae adjacent to the lumen appears to be protective against ascending aortic dilatation." (PMID 38545339, 2024).
Ascending aortic dissection (1 paper, 2020). A separation of the layers within the wall of the ascending aorta. "Decreased elastin concentrations within the aortic wall are strongly correlated with decreased expression of Fbln5 in patients with ascending aortic dissection, similar to our findings using Nos3−/− mice." (PMID 32801116, 2020).
asthma (1 paper, 2025). "In contrast, fibulin-5 seems to perpetuate fibrosis, at least in part, independently of TGFβ by increasing tissue stiffness, with results from asthma patients suggesting a fibulin-5-mediated modulation of the YAP/TAZ and Hippo pathway based on β1 integrin binding in airway smooth muscle cells." (PMID 41362624, 2025).
astrocytoma (1 paper, 2019). "Fibulin-1 (FBLN1) was described as being up-regulated in high-grade astrocytoma, and Fibulin-2 (FBLN2) and Fibulin-5 (FBLN5) was described as being down-regulated in grade II/III/IV compared with grade I astrocytoma." (PMID 31357616, 2019).
ataxia telangiectasia (1 paper, 2025). Ataxia-telangiectasia is the association of severe combined immunodeficiency (affecting mainly the humoral immune response) with progressive cerebellar ataxia. "The discovery of a novel FBLN5 variant expands the mutational landscape of cutis laxa type 1A, while the ATM variant broadens phenotypic recognition of ataxia telangiectasia." (PMID 41300699, 2025).
autoimmune disease (1 paper, 2015). A disorder resulting from loss of function or tissue destruction of an organ or multiple organs, arising from humoral or cellular immune responses of the individual to their own tissue constituents. "Interestingly, Fibulin-5 RNA and proteinlevels are also increased in the skin of patients with systemic scleroderma, aprogressive autoimmune disease in which fibrosis is a defining feature." (PMID 26469761, 2015).
calcification (1 paper, 2022). Process by which organic tissue becomes hardened by the physiologic deposit of calcium salts. "Numerous studies have confirmed that FBLN5 has predictive value for the outcome of coronary calcification." (PMID 35356421, 2022).
cerebral aneurysms (1 paper, 2022). "The control samples were obtained from 10 patients with unruptured cerebral aneurysms, but one patient’s data were excluded because active gingivitis was associated and thereby the plasma FBLN5 levels were extremely high (899.0 ng/mL; Smirnov–Grubbs’s test, p = 0.03)." (PMID 36499510, 2022).
cerebral infarction (1 paper, 2022). An ischemic condition of the brain, producing a persistent focal neurological deficit in the area of distribution of the cerebral arteries. "Plasma FBLN5 levels were not related to angiographic vasospasm, delayed cerebral ischemia, and delayed cerebral infarction, but elevated levels were associated with severe admission clinical grades, any neurological exacerbation and poor outcomes." (PMID 36499510, 2022). "Plasma FBLN5 levels were not different among the modified Fisher grades, and between patients with and without an angiographic vasospasm, a DCI, and a delayed cerebral infarction, at any sampling point." (PMID 36499510, 2022).
chordoma (1 paper, 2015). Chordomas are rare malignant tumors arising from embryonic remnants of the notochord in axial skeleton. "In the exophytic chordoma tissues, the expression of tumor cell motility-associated proteins such as TGFβ1, HGDF, THBS2 and FBLN5 were significantly higher than that of the endophytic type." (PMID 25793716, 2015).
chronic hepatitis C (1 paper, 2026). "We then investigated the plasma level of FBLN5 in 67 patients with chronic hepatitis C. Depending on the fibrosis stage, plasma FBLN5 levels increased with disease progression (P < .001), whereas plasma FBLN5 levels did not increase in association with activity grade (data not shown)." (PMID 41362817, 2026). "Finally, plasma FBLN5 levels increased with fibrosis progression in patients with chronic hepatitis C (P < .001)." (PMID 41362817, 2026).
Cirrhosis (1 paper, 2026). A chronic disorder of the liver in which liver tissue becomes scarred and is partially replaced by regenerative nodules and fibrotic tissue resulting in loss of liver function. "FBLN5 showed significant predictability both for the prediction of advanced fibrosis (area under the receiver-operating characteristic [AUROC] curve: 0.845) and cirrhosis (AUROC curve: 0.823)." (PMID 41362817, 2026).
gastric tumors (1 paper, 2025). "In addition, plasma FBLN5 concentration positively correlated with FBLN5 protein expression of the primary tumor tissue, indicating that plasma fibulin-5 levels represent its expression in gastric tumors." (PMID 40369121, 2025).
Glucose intolerance (1 paper, 2025). Glucose intolerance (GI) can be defined as dysglycemia that comprises both prediabetes and diabetes. "Fbln5 deletion in β-cells caused slight glucose intolerance in βFbln5KO mice at 3 and 12 weeks of age without impaired insulin secretion." (PMID 39995864, 2025).
Hydrocephalus (1 paper, 2025). Hydrocephalus is an active distension of the ventricular system of the brain resulting from inadequate passage of CSF from its point of production within the cerebral ventricles to its point of absorption into the systemic circulation. "This study aimed to investigate whether the administration of recombinant FBLN5 (rFBLN5) influences the development of hydrocephalus following SAH in mice and whether this effect is associated with changes in PVMs." (PMID 40943182, 2025). "This study aimed to investigate whether and how FBLN5 was associated with hydrocephalus during acute to later phases of SAH in mice." (PMID 40943182, 2025). "However, this is the first study to experimentally show the relationship between FBLN5, PVM, and hydrocephalus." (PMID 40943182, 2025).
Hyperglycemia (1 paper, 2017). An increased concentration of glucose in the blood. "Chronic hyperglycemia in Irs-2−/− mouse may cause the elevation in Fbln5 in the islets at the basal state." (PMID 28539593, 2017).
insulinoma (1 paper, 2017). "We detected FBLN5 protein expression in the wild-type mouse islets, as well as in INS-1 rat insulinoma cell line but not in the Fbln5-deficient (Fbln5−/−) islets." (PMID 28539593, 2017).
intracranial aneurysms (1 paper, 2022). "In SAH, FBLN5 may increase the reflecting of the rupture of intracranial aneurysms or vessel injuries, associated with an angiographic vasospasm, but the findings in this study did not support the hypothesis." (PMID 36499510, 2022).
keratoconus (1 paper, 2022). A degenerative, structural disorder of the eye, characterized by a cone-shaped protrusion of the cornea. "And some of their target genes, such as FN1, COL12A1, TIMP3 and FBLN5, were associated with ECM and also down-regulated in keratoconus." (PMID 35821117, 2022).
liver disease (1 paper, 2026). "A comprehensive microarray analysis that compared mild (F0-1) and severe (F3–4) steatotic liver disease showed that FBLN5 was upregulated in severe steatotic liver disease along with collagen species." (PMID 41362817, 2026). "FBLN5-expressing cells were distributed within the HSC/fibroblast cluster on the UMAP, and the expression level was higher in cirrhotic livers with steatohepatitis compared to steatotic liver disease or normal livers." (PMID 41362817, 2026).
macular degeneration (1 paper, 2016). Loss of vision in the central portion of the retina (macula), secondary to retinal degeneration. "In eight sporadic cases, we detected eight heterozygous rare sequence variants in six macular degeneration genes (CFH; FBLN1, OMIM 135820; FBLN3/EFEMP1, OMIM 601548; FBLN5, OMIM 604580; HMCN1, OMIM 608548; FBN2, OMIM 612570)." (PMID 27007659, 2016).
macular dystrophies (1 paper, 2011). "In addition to fibulin 5, other fibulin proteins are implicated in macular dystrophies." (PMID 21829675, 2011).
mucinous adenocarcinoma (1 paper, 2023). An invasive adenocarcinoma composed of malignant glandular cells which contain intracytoplasmic mucin. "In addition, in mucinous adenocarcinoma, FBLN5 is highly expressed in the cytoplasm of cancer cells and interstitial fibroblasts." (PMID 36672502, 2023).
myocardial infarction (1 paper, 2020). Gross necrosis of the myocardium, as a result of interruption of the blood supply to the area, as in coronary thrombosis. "IL-35 spares regenerative angiogenesis after 14 dpi in HLI by anti-ROS regulator Fbln5, which are well correlated with recent reports that IL-35 is protective in myocardial infarction-induced injury." (PMID 33154757, 2020).
ocular hypertension (1 paper, 2024). Abnormally high intraocular pressure. "Gene expression of signature astrocyte reactivity markers (Gfap, Lcn2, Steap4, Gbp2, Serping1, and Fbln5) were significantly upregulated in response to ocular hypertension at 2, 4, and 8 weeks compared to that in normotensive controls." (PMID 38610040, 2024).
oral cancer (1 paper, 2022). "A panel of five genes (MMP1, FBLN5, COL5A3, BGN and LOXL1) was useful for predication the successful grafters among oral cancer patients." (PMID 35444950, 2022).
prostate tumors (1 paper, 2013). "All analyses, microarray, immunohistochemistry (IHC), and RT-PCR consistently suggested down-regulation of FBLN5 in prostate tumors." (PMID 23593148, 2013).
pseudoexfoliation glaucoma (1 paper, 2023). "Genetic association and risk haplotype analysis showed a significant association of rs17732466:G>A (NC_000014.9:g.91913280G>A) and rs72705342:C>T (NC_000014.9:g.91890855C>T) within FBLN5 as risk factors with the advanced severe stage of the disease, pseudoexfoliation glaucoma (PEXG)." (PMID 36794549, 2023).
pterygium (1 paper, 2021). A wedge-shaped fibrovascular lesion arising from the bulbar conjunctiva and extending to the cornea. "The subepithelial connective tissue shows weak immunolabeling for FBLN5 in healthy conjunctiva, while the levels are significantly increased in pterygium, which show very marked areas of degenerative elastogenic changes or immature fiber formation." (PMID 34945227, 2021).
pulmonary embolism (1 paper, 2024). The obstruction of the pulmonary artery or one of its branches by an embolus, sometimes associated with infarction of the lung. "Recent studies have suggested that FBLN5 may play a role in thrombosis and pulmonary embolism." (PMID 38649864, 2024).
pulmonary hypertension (1 paper, 2015). Increased pressure within the pulmonary circulation due to lung or heart disorder. "For example, altered fibulin-5 expression has been linked to lung injury and pulmonary hypertension." (PMID 25909283, 2015).
renal carcinoma (1 paper, 2023). A carcinoma arising from the epithelium of the renal parenchyma or the renal pelvis. "SPTAN1 and FBLN5 are favorable prognostic markers in renal cancer but unfavorable in OC (considering a p < 0.05)." (PMID 37775701, 2023).
retinal disease (1 paper, 2021). "In addition, other retinal disease-causing genes related to AMD were mainly expressed in clusters P4, P6 and P7, but some susceptibility genes, such as C2, FBLN5, and TLR4, were highly expressed in the macular cluster." (PMID 34977041, 2021).
retinopathy of prematurity (1 paper, 2017). A bilateral retinopathy characterized by neovascularization, scarring, retinal detachment, and eventually blindness. "Estimated haplotype frequencies of the significantly associated variants in CETP, CFH, and FBLN5 genes in retinopathy of prematurity (ROP) and premature controls." (PMID 29312345, 2017).
skin aging (1 paper, 2023). The gradual irreversible changes in structure of skin that occur as a result of the passage of time.. "Data from other researchers have shown that Fibulin 5, a glycoprotein involved in the induction of elastic fiber assembly and maturation, can be a useful marker of skin aging." (PMID 37371754, 2023).
supravalvular aortic stenosis (1 paper, 2022). SupraValvar Aortic Stenosis (SVAS) is characterized by the narrowing of the aorta lumen (close to its origin) or other arteries (branch pulmonary arteries, coronary arteries). "Mutations in fibulin-4 were linked to autosomal recessive cutis laxa type IB, associated with aortic dissection, and mutations in fibulin-5 with autosomal recessive cutis laxa type IA, associated with supravalvular aortic stenosis (SVAS) and peripheral pulmonary artery stenosis." (PMID 35216218, 2022).
thrombosis (1 paper, 2024). "Subsequent screening revealed that the procoagulant-related protein von vWF plays a crucial role in network regulation along with FBLN5, a protein closely associated with thrombosis." (PMID 38649864, 2024). "Additionally, vWF/FBLN5 upregulation may be a novel mechanism for virus-associated thrombosis/coagulation." (PMID 38649864, 2024). "Together with our results, these findings suggest that vWF/FBLN-5 disorder-induced thrombosis and vascular injury may be interrelated, or rather, thrombosis and vascular damage occur together." (PMID 38649864, 2024).
thyroid cancer (1 paper, 2022). "FBLN5 expression was found to be underexpressed in thyroid cancer and was enhanced and reduced by LINC00987 overexpression and miR-27b-3p overexpression, respectively." (PMID 36306007, 2022). "Here, FBLN5 was found to be underexpressed in thyroid cancer, and its expression was enhanced by LINC00987 overexpression." (PMID 36306007, 2022). "Among the 14 potential target genes, FBLN5 mRNA expression was significantly decreased in thyroid cancer, as determined by GEPIA analysis." (PMID 36306007, 2022). "FBLN5 was discovered in this study to be the targeted gene of miR-27b-3p in thyroid cancer." (PMID 36306007, 2022). "Furthermore, FBLN5 knockdown promoted the malignant progression of thyroid cancer cells by counteracting the effect of LINC00987." (PMID 36306007, 2022). "Next, we investigated whether FBLN5 is involved in the influence of LINC01089 on the biological function of thyroid cancer." (PMID 36306007, 2022). "Fibulin-5 (FBLN5) was discovered as a target of miR-27b-3p in thyroid cancer." (PMID 36306007, 2022). "Furthermore, the knockdown of FBLN5 promoted the malignant progression of thyroid cancer cells, reversing the effect of LINC00987." (PMID 36306007, 2022). "Whether FBLN5 acts downstream of LINC01089 regulation in thyroid cancer is unclear." (PMID 36306007, 2022). "In addition, the FBLN5 protein level was significantly decreased in both thyroid cancer cells." (PMID 36306007, 2022). "In conclusion, LINC01089 plays a tumor-suppressive role by binding miR-27b-3p to increase FBLN5 expression, confirming that LINC01089 has tremendous potential to become a therapeutic target for thyroid cancer treatment." (PMID 36306007, 2022). "In conclusion, LINC01089 plays a tumor-suppressive role in malignant progression by inhibiting miR-27b-3p and increasing FBLN5 protein, confirming that LINC01089 has tremendous potential for use in the treatment of thyroid cancer." (PMID 36306007, 2022). "In addition, FBLN5 expression was reduced by miR-27b-3p overexpression, suggesting that FBLN5 is the downstream target gene of LINC00987 in thyroid cancer." (PMID 36306007, 2022). "Combined with the regulatory relationship between miR-27b-3 and FBLN5 and the adsorption relationship between LINC01089 and miR-27b-3p, these results suggested that LINC01089 upregulates the expression of FBLN5 by adsorbing miR-27b-3p and exerts a tumor suppressor function in thyroid cancer." (PMID 36306007, 2022).
Uterine leiomyoma (1 paper, 2021). The presence of a leiomyoma of the uterus. "It has been reported that miR-200c is overexpressed in uterine leiomyoma by targeting FBLN5." (PMID 34475958, 2021).
uterine prolapse (1 paper, 2016). Downward displacement of the UTERUS. "We expected that failed up-regulation of Fbln5 in the vagina after injury or parturition would lead to the development of vaginal/uterine prolapse due to a failure of proper elastic fiber remodeling (i.e., rebuilding of the elastic fiber network)." (PMID 27124299, 2016).
ventricular dilatation (1 paper, 2025). "This study first revealed that exogenous administration of FBLN5 may have a protective effect against ventricular dilatation after experimental SAH." (PMID 40943182, 2025). "Although further research is required to clarify the detailed mechanism, this study demonstrated for the first time that exogenous administration of FBLN5 may have a protective effect against ventricular dilatation after experimental SAH." (PMID 40943182, 2025).